FAP (fibroblast activation protein alpha)
Diseases named in the same sentence as FAP in open-access papers (continued):
Sharing a sentence is not in itself a finding about the gene and the disease.
pancreatic cancer (continued). "Because of this topographical similarity to that of tumor permissive 3D ECMs, the FAP+ 3D matrix system was used to study the mechanism of matrix-supported pancreatic cancer cell invasion." (PMID 21668992, 2011). "Research has shown that the adoptive transfer of FAP-CAR -T cells diminishes tumor growth in a FAP-dependent manner and can eliminate stromal cells, evident in several solid tumors, including mesothelioma, lung cancer, and pancreatic cancer, demonstrating antitumor activity in preclinical models." (PMID 40861448, 2025). "Moreover, the ablation of FAP+α‐SMA+ CAFs in pancreatic cancer has paradoxically accelerated tumor progression, highlighting the complexity and potential risks of indiscriminate CAF targeting." (PMID 40656546, 2025). "In pancreatic cancer, for instance, the ablation of FAP+ CAFs has paradoxically led to accelerated tumor progression and increased Treg cell infiltration, raising concerns about the safety and effectiveness of directly targeting FAP and α‐SMA." (PMID 40656546, 2025). "Furthermore, some cancer cells (e.g., sarcoma, certain ovarian, and pancreatic cancers) can exhibit FAP expression as well." (PMID 38540204, 2024). "In pancreatic cancer, FAP is expressed not only on CAFs but also on the tumoral cells themselves." (PMID 38540204, 2024). "Fibroblast activation protein-α (FAP) is selectively expressed in interstitial fibroblasts in more than 90% of malignant epithelial tumors, such as breast cancer, ovarian cancer, gastric cancer, colon cancer, pancreatic cancer, and cutaneous melanoma." (PMID 38740736, 2024). "Previous experiments on pancreatic cancer have shown that targeting FAP could not only improve the body’s antitumor immune function but also enhance the efficacy of antitumor drugs." (PMID 38740736, 2024). "Based on these properties, 131I-labeled FAP-2286 may serve as a good TRT agent for pancreatic cancer, and certainly, strategies to further improve the therapeutic effect is warranted." (PMID 38360704, 2024). "Evidence suggests that a significant portion of CAFs may originate from MSCs, which can differentiate and express CAF markers, such as vimentin and FAP when exposed to conditioned media from various human cancer cell cultures like pancreatic cancer." (PMID 38835055, 2024). "However, recent studies also showed that FAP can be overexpressed on cancer cells themselves, among others also in human-derived pancreatic cancer cell lines." (PMID 38672617, 2024). "FAP+ CAFs hinder the anti-tumor activity of T cells in pancreatic cancer." (PMID 38835055, 2024). "Further study showed that FAP-positive CAFs promoted proinflammatory gene expression and may be involved in tumor immune evasion in a mouse model of pancreatic cancer." (PMID 38017374, 2023). "Although some side-effects like enhanced tumor hypoxia and Treg infiltration may arise with α-SMA targeting, FAP-targeting strategies show significant antitumor efficacy in preclinical models of lung, colon and pancreatic cancers." (PMID 37784157, 2023). "In addition, overexpression of FAP in fibroblasts leads to an alteration of the extracellular matrix and enhances the invasiveness of pancreatic cancer cells." (PMID 37174079, 2023). "Similarly, our bioinformatic analysis revealed the correlation between FAP expression and MDSCs in pancreatic cancer patients in the TCGA database, further proving the crosstalk of those two types of cells in TME." (PMID 37046312, 2023). "Fibroblast activation protein α (FAP) is a serine protease with dipeptidyl peptidase and gelatinase activity that is expressed by CAFs in over 90 percent of epithelial cancers, including pancreatic cancer." (PMID 37174079, 2023). "In addition, pancreatic stellate cells mainly undergo FAP overexpression by inducing pancreatic cancer cells-released TGFβ1." (PMID 37316886, 2023).
pancreatic cancer (continued). "Hence, most tumors show FAP expression in the TME, while some cancers actually express FAP on their cellular membrane (e.g., sarcoma, certain ovarian, and pancreatic cancers)." (PMID 36813980, 2023). "Moreover, it has been reported that high FAP expression in pancreatic cancer patients resulted in lymph node metastasis and shorter survival." (PMID 37316886, 2023). "The high levels of FAP expression in pancreatic cancer stroma have also been correlated with the poor prognosis of patients and desmoplasia, and FAP has been identified as an independent predictor of pancreatic cancer survival." (PMID 36263225, 2022). "GPC1 is also expressed on FAP-positive CAFs in pancreatic cancer." (PMID 35159011, 2022). "Finally, we assess the emerging basic and clinical studies regarding the bench-to-bedside translation of FAP in pancreatic cancer." (PMID 36263225, 2022). "Beta therapy and alpha therapy targeting FAP can be a potential treatment for pancreatic cancers and needs further evaluation to find the best combination of fast FAP kinetics and physical decay of the radionuclide as well as the combination with therapies targeting tumour cells." (PMID 34537893, 2022). "Thus, 64Cu-FAPI-04 and 225Ac-FAPI-04 can be used as a pair radioligands for theranostic of FAP-expressing pancreatic cancer." (PMID 35059319, 2021). "Adoptive transfer of chimeric antigen receptor (CAR) T cells directed to FAP inhibited pancreatic cancer cell growth, but infusion of FAP reactive CAR T cells has also been reported to trigger bone marrow toxicity and cachexia, a condition often seen in advanced PDAC." (PMID 34203869, 2021). "However, additional markers are further required to increase specificity for FAP-positive CAFs in pancreatic cancer." (PMID 33572223, 2021). "Using flow cytometry, FAP has been found in a subset of pancreatic cancer cell." (PMID 34035230, 2021). "In line with this, conditional ablation of FAP-positive cells (using Diphtheria Toxin Receptor (DTR) expressing selectively in FAP-positive cells) introduced into the KPC mouse line leads to inhibition of pancreatic tumor development." (PMID 33572223, 2021). "Adoptive transfer of anti-FAP CAR T cells inhibits the growth of pancreatic cancers in KPC mice." (PMID 33572223, 2021). "FAP is frequently (90%) expressed, predominantly in CAFs, in patients with pancreatic cancer." (PMID 33572223, 2021). "Depleting FAP-expressing cells allowed for immunological-controlled growth in pancreatic cancer." (PMID 33634030, 2020). "FAP is also noted to allow pancreatic cancer cells to escape immune surveillance." (PMID 32466266, 2020). "FAP+ CAFs are the primary pancreatic cancer source of the chemokine ligand 12 (CXCL12)." (PMID 32466266, 2020). "Additionally, the adoptive transfer of FAP-specific CAR T cells can arrest pancreatic cancer growth with low immunogenicity and high desmoplasia." (PMID 31462327, 2019). "Additionally, the migration and proliferation of pancreatic cancer is also supported by CAFs expressing fibroblast activation proteins (FAP)." (PMID 30987642, 2019). "FAP is also present in a large proportion of tumor stromal fibroblasts in the majority of epithelial carcinomas including pancreatic cancers and its expression correlates with poor prognosis in pancreatic cancer patients." (PMID 30809507, 2019). "Indeed CAR T cells that target the highly expressed CAF protein, FAP, are considered in pancreatic cancer due to the significant role these cells play in tumorigenesis and in addition, FAP is positive in PDAC-derived ECMs but negative in normal PSCs." (PMID 30809507, 2019). "A series of findings about the expression and role of FAP α in pancreatic carcinoma has suggested that FAP α-targeted immunotherapy may be a new treatment for pancreatic cancer patients." (PMID 26985769, 2016). "Thus, FAP-expressing fibroblasts are critical for remodeling a permissive stromal environment that supports pancreatic cancer progression." (PMID 26330349, 2015).
pancreatic cancer (continued). "One was the effect of FAP on the invasiveness of pancreatic cancer cells." (PMID 26330349, 2015). "Therefore, further studies including assessment of the effect of FAP on G1-Cdk expression/activity are required to clarify how FAP-expressing fibroblasts activate phosphorylation of Rb protein in pancreatic cancer cells." (PMID 26330349, 2015). "Depletion of the cells expressing FAP-α enabled immune response-associated tumor regression, supporting the notion that FAP-α might act as an immune suppressor in pancreatic cancer." (PMID 24592240, 2014). "Here, we show that FAP enzymatic activity locally modifies stromal ECM components thus facilitating the formation of a permissive microenvironment promoting tumor invasion on human pancreatic cancer." (PMID 21668992, 2011). "The results demonstrate that FAP+ matrix effects may be important in neoplasias other than just pancreatic cancers." (PMID 21668992, 2011). "Given the incomplete abrogation of invasive behavior of Panc-1 cells in the presence of ATN-161, it is possible that additional β1-integrins could also contribute to pancreatic cancer invasion facilitated by the FAP+ 3D matrices." (PMID 21668992, 2011). "In order to question whether FAP+ matrix effects promoting cell motility of invasive pancreatic cancer cells (i.e., Panc-1) are specific for pancreatic cancers, we repeated this series of experiments using three well characterized breast cell lines." (PMID 21668992, 2011). "For example, tumors characterized by a dense desmoplastic reaction, such as sarcomas, pancreatic cancers, and lung adenocarcinomas, demonstrate robust FAP expression which results in high tumor-to-background contrast that may surpass the performance of FDG PET." (PMID 41441395, 2025). "Notably, FAP is overexpressed in fibroblasts of a wide range of malignant tumors, especially those with a strong connective tissue proliferative response, such as breast, colon, and pancreatic cancers." (PMID 40430845, 2025). "It was demonstrated that pancreatic cancers have two characteristic fibroblasts subpopulations, namely myofibroblastic ones based on the expression of αSMA (myCAFs) and an inflammatory subset (iCAFs) based on fibroblast activation protein (FAP) expression, amongst other markers." (PMID 38891809, 2024). "Interestingly, the pancreatic cancer cells express endogenous FAP." (PMID 38891809, 2024). "For example, the clearance of FAP+ CAFs by chimeric antigen engineered T cells reduced the desmoplastic stromal structure and tumour vascular density, resulting in significant anti‐tumour effects in human lung cancer xenografts and syngeneic murine pancreatic cancers." (PMID 38115703, 2023). "Thus, pancreatic cancer is expected to show intense FAP expression." (PMID 37608378, 2023). "Therefore, this study has completed the construction of dual-recognition specific antibodies (anti-EGFR antibody for pancreatic cancer cells and anti-FAP for fibroblasts surrounding pancreatic cancer cells), which remove the Fc fragment and preserve the specific target region, Fv fragments." (PMID 35745775, 2022). "PTRT with 177Lu-FAP-2286 appears to ameliorate symptoms in rapidly proliferating adenocarcinomas as noted by significant pain reduction in patient 4, with liver metastases; patient 6, with diffuse bone metastases; and patient 5, with newly diagnosed pancreatic cancer." (PMID 34168013, 2022). "The association between FAP overexpression and a detrimental OS in colorectal cancers and pancreatic cancers is similar to that observed for pooled non-colorectal cancers and non-pancreatic cancers, respectively." (PMID 25775399, 2015). "We tested the hypothesis that FAP enzymatic activity locally modifies stromal ECM (extracellular matrix) components thus facilitating the formation of a permissive microenvironment promoting tumor invasion in human pancreatic cancer." (PMID 21668992, 2011).
pancreatic cancer (continued). "Ongoing exploration of novel or optimized targets includes B7-H3 and GD2 for brain cancer, MSLN and CEA for pancreatic cancer, MSLN and FAP for mesothelioma, and GPC3 for liver cancer." (PMID 40969260, 2025). "designed and developed 68 Ga- and 18F- labeled molecular tracers targeting the FAP and αvβ3 dual-specific heterodimer FAPI-RGD, demonstrating its superiority over mono targets in human pancreatic cancer tumor-bearing mouse model." (PMID 40048021, 2025). "Cancer stem cells (CSCs) hijack stromal signaling to evade immunity and support metastasis, particularly in breast and pancreatic cancers, where CSC–fibroblast crosstalk via IL-6 and FAP plays a critical role." (PMID 40643502, 2025). "A recent investigation revealed that pancreatic cancer exhibits high FAPI avidity, with immunohistochemical staining confirming that this uptake directly correlates with tumoral FAP expression levels." (PMID 40457405, 2025). "Next to U-87 MG, other cell lines have been used to create a FAP-positive CDX based on attracting murine fibroblasts, including the pancreatic cancer cell lines Panc-1 and PDAC299." (PMID 39718718, 2024). "In this study, 131I-labeled FAP-2286-Tyr, abbreviate as 131I-FAP-2286, was developed for the TRT in pancreatic cancer." (PMID 38360704, 2024). "According to the immunohistochemistry assay, the expression of α-SMA, a well-known marker of CAFs, was consistent with FAP in the pancreatic cancer xenograft model with the co-injection of PANC-1 and CAFs, confirming the presence of abundant FAP-positive CAFs." (PMID 38360704, 2024). "Given the significant presence of CAFs in PDAC, intensive uptake of Gallium-68 FAP inhibitor (Ga68-FAPI) is expected, as demonstrated in previous studies showing a promising clinical value of Ga68-FAPI PET/CT for pancreatic cancer diagnosis." (PMID 38540204, 2024). "FAP-directed CAR-T cells have been developed to target CAFs in several solid tumors, including mesothelioma, lung cancer, and pancreatic cancer, demonstrating antitumor activity in preclinical models." (PMID 38727261, 2024). "Herein, FAP-targeted RLT is a promising strategy for FAP-positive or stroma-rich tumors, such as sarcoma directly expressing FAP on the tumor cells or pancreatic cancers with abundant stroma." (PMID 38706713, 2023). "FAP + PSCs released the chemokine (C-X-C motif) ligand 1 (CXCL1) and promoted the phosphorylation of the tyrosine kinase receptors EphB1 and EphB3 in pancreatic cancer cells." (PMID 37316886, 2023). "Correlated with the high FAP expression in tissue, high uptake on FAPI PET has been demonstrated in pancreatic cancer." (PMID 37608378, 2023). "At present, the most promising clinical data of FAP TRT was reported in advanced sarcoma, breast, thyroid, and pancreatic cancer." (PMID 36813980, 2023). "Since FAP and PSMA are both expressed in prostate cancer and other cancers such as pancreatic cancer, the use of PSMA/FAP bispecific radioligands is expected to increase lesion detection sensitivity and treatment efficacy." (PMID 36770755, 2023). "These analyses revealed that FAP expression in CRC is most closely related to FAP- and ACTA2-expressing stromal cells in pancreatic cancer (R2 = 0.53 and 0.55, respectively) and least to inflammatory CAFs (R2 = 0.06)." (PMID 35296803, 2022). "COL1A1, COL1A2, ACTA2, PDGFRB and FAP displayed a significant positive correlation with this gene dataset in melanoma tumours (SKCM), whereas in pancreatic tumours (PAAD), that correlation was even stronger owing to their highly desmoplastic TME." (PMID 35654839, 2022). "The majority of fibroblasts in human pancreatic tumors and in tumors from KPC mice express FAP but low levels of α-SMA." (PMID 35159011, 2022). "The adoptive transfer of FAP–CAR-T cells restrained the growth of desmoplastic human lung cancer xenografts, syngeneic murine pancreatic cancers, and autochthonous pancreatic cancer growth in an immune-dependent fashion." (PMID 35014625, 2022).
pancreatic cancer (continued). "In pancreatic cancer, the CXCL12 chemokine derived from FAP-expressing CAFs has gained recognition as an attractive therapeutic target." (PMID 35805064, 2022). "According to the literature, the expression of the FAP, CXCL12, CTGF, and SNAI1 genes is characteristic of CAFs in the TME of pancreatic cancer." (PMID 33804861, 2021). "The majority of fibroblasts in human pancreatic tumors as well as in tumors from KPC mice express FAP and low levels of α-SMA, whereas a subpopulation of FAP-positive cells exhibit elevated α-SMA expression called myofibroblastic CAFs (myCAFs)." (PMID 33572223, 2021). "The efficacy of [68Ga]Ga-FAPI-02, the first generation of FAP inhibitors was investigated in comparison with the reference standard [18F]FDG in patients with breast, lung, and pancreatic cancer metastases." (PMID 34681246, 2021). "This work demonstrates the potential clinical utility of CD8 and FAP in PDAC patients, and it sheds light on the expression patterns of CD200 in pancreatic cancer as the protein is being tested as a target for immune checkpoint blockade." (PMID 34771664, 2021). "The iCAF subpopulation is detected in invasive pancreatic cancer, and iCAFs exhibit elevated expression of VIM, FAP, COL3A1, DES, IL6, and CXCL12 and reduced expression of ACTA2 (coding α-SMA)." (PMID 33333727, 2020). "To date, eight studies have demonstrated antitumor activity of FAP-targeting CAR-T cells in several preclinical models including mesothelioma, lung, mammary, colon, pancreatic cancers, with a key measure of these studies being the potential for toxicity." (PMID 32625204, 2020). "Fibroblast Activation Protein Alpha (FAP) was proven to serve as a marker in metastatic prostate cancer, pancreatic cancer and ovarian cancer." (PMID 33614471, 2020). "In contrary, Feig C. demonstrated that the depletion of FAP-expressing cells, by conditional ablation of FAP+ cells using diphtheria toxin led to an increase in anti-tumorigenic cytotoxic CD8+ T cells, slowing the pancreatic tumor growth." (PMID 32781778, 2020). "In the context of CARs, several groups have generated fibroblast activation protein (FAP)-redirected CAR T cells to erase FAP-expressing CAFs, resulting in a reduction of ECM molecules and tumour growth, also in a syngeneic murine pancreatic cancer model." (PMID 32481570, 2020). "In two different studies, using either genetic FAP ablation or a DNA vaccine directed against FAP, improved recruitment of CD8+ T-cells and prolonged survival in murine models of lung, colon and pancreatic cancer." (PMID 31731701, 2019). "For example, a recent publication demonstrates that targeting the CXCL12-CXCR4 axis with AMD3100 (Plerixafor) reverses FAP+ CAF-mediated immunosuppression and synergizes with anti-PD-L1 immunotherapy in pancreatic cancer." (PMID 31462327, 2019). "Targeting of other tumor antigens such as CEA (carcinoembryonic antigen), FAP, and mucin (MUC)-1 also has marked activity in murine models of pancreatic cancer." (PMID 30987642, 2019). "We cultured CAFs with CM from either control pancreatic cancer cells or SATB-1-silenced pancreatic cancer cells and analyzed the α-SMA and FAP expression levels in CAFs." (PMID 30337520, 2018). "In pancreatic carcinoma, FAP α is not only expressed in stromal fibroblast cells, but also in carcinoma cells, in contrast to previous studies which had shown FAP α to be selectively expressed in malignant cells of bone and soft tissue sarcomas." (PMID 26985769, 2016). "Although this issue is still controversial, we successfully amplified the hFAP cDNA by PCR using BxPC-3 (a pancreatic cancer cell line) mRNA as a template and specific hfap primers, and established NIH-3 T3 cells that stably expressed human FAP." (PMID 26330349, 2015). "In xenograft mouse models inoculating the human pancreatic cancer cell lines (HPAF-II, Capan-1, AsPC-1, and Panc-1), murine FAP expression was also found up-regulated specifically at the tumor stroma." (PMID 21668992, 2011).